RNU1-58P (RNA, U1 small nuclear 58, pseudogene)
Gene: Small nuclear RNA gene on chromosome 7 (140,241,870 to 140,242,032, forward strand). Ensembl gene ENSG00000199283.
Homologues: Orthologues: chimpanzee U1 (99% identical), macaque U1 (93% identical), macaque U1 (91% identical), rabbit U1 (80% identical), rat LOC120094894 (80% identical), guinea pig U1 (76% identical), pig U1 (67% identical). Paralogues in human: RNU1-138P (83% identical), RNU1-1 (82% identical), RNU1-2 (82% identical), RNU1-27P (82% identical), RNU1-28P (82% identical), RNU1-3 (82% identical), RNU1-4 (82% identical), RNVU1-18 (82% identical), RNVU1-28 (82% identical), RNVU1-29 (82% identical), U1 (82% identical), RNU1-89P (82% identical), and 134 more.